SOX5 (SRY-box transcription factor 5)
Diseases named in the same sentence as SOX5 in open-access papers (continued):
Sharing a sentence is not in itself a finding about the gene and the disease.
achondroplasia (1 paper, 2008). Achondroplasia is the most common form of chondrodysplasia, characterized by rhizomelia, exaggerated lumbar lordosis, brachydactyly, and macrocephaly with frontal bossing and midface hypoplasia. "The gain-of-function mutant of Fgfr3 causes achondroplasia, Sox9 controls chondrocyte differentiation via Sox5 and Sox6 expression, and Ihh is a master gene of bone development under BMP control, suggesting that Slc39a13 exerts a profound influence on genes crucial to chondrocyte differentiation." (PMID 18985159, 2008).
Alzheimer disease (1 paper, 2025). A progressive, neurodegenerative disease characterized by loss of function and death of nerve cells in several areas of the brain leading to loss of cognitive function such as memory and language. "Previous research has documented that, despite a positive family history of late-onset Alzheimer's disease (LOAD), the SOX5 variant (c.221C > T, p.Thr74Met) was detected in healthy individuals, and this variant was thus interpreted as being protective." (PMID 39905544, 2025).
amyotrophic lateral sclerosis (1 paper, 2024). Amyotrophic lateral sclerosis (ALS) is a neurodegenerative disease characterized by progressive muscular paralysis reflecting degeneration of motor neurons in the primary motor cortex, corticospinal tracts, brainstem and spinal cord. "Upon comparing both types of sporadic FTD patients, we found a DMP in the SOX5 gene, a gene involved in corticospinal motor neuron development and a known risk factor for developing amyotrophic lateral sclerosis (ALS)." (PMID 38791483, 2024).
apraxia (1 paper, 2024). Apraxia is a neurological disorder characterized by the inability to perform tasks or movements, despite having the desire and physical ability to perform them. "In addition, Lmo4 and Sox5, which have been shown to participate in neuron differentiation with SOX5 being clinically associated with an NDD with apraxia of speech." (PMID 38238293, 2024).
B-cell neoplasm (1 paper, 2015). A group of heterogeneous lymphoid tumors generally expressing one or more B-cell antigens or representing malignant transformations of B-lymphocytes. "However, whether SOX5 can serve as a therapeutic target in human B cell neoplasms involving TRAF3 inactivation or aberrant SOX5 expression awaits further investigation." (PMID 25960828, 2015).
brain tumors (1 paper, 2014). "SOX5 encodes a high mobility group protein with a role in cell differentiation, and it has been isolated as a target of retroviral insertional mutagenesis in mouse brain tumors." (PMID 25227228, 2014).
cartilage disease (1 paper, 2024). Softening and degeneration of the CARTILAGE. "Past research has reported that PACAP play an important role in cartilage diseases by regulating SOX family member molecules such as SOX5, SOX6, SOX9." (PMID 39619607, 2024).
Cerebral ischemia (1 paper, 2025). Restriction of arterial blood supply to the brain associated with insufficient oxygenation to support the metabolic requirements of the tissue. "SOX5, previously reported to reverse nerve injury by cerebral ischemia via activation of the PI3K/AKT pathway." (PMID 41331264, 2025).
Cirrhosis (1 paper, 2025). A chronic disorder of the liver in which liver tissue becomes scarred and is partially replaced by regenerative nodules and fibrotic tissue resulting in loss of liver function. "Although it was found to be upregulated in HCC and other cancers, we found SOX5 to be decreased in NAFLD and lowest in cirrhosis when compared to healthy controls." (PMID 40489530, 2025).
common variable immunodeficiency (1 paper, 2014). "Later, dysregulation of SOX5 gene expression was reported in the innate-like CD21low B-cell subpopulation of patients with common variable immunodeficiency (CVID) and patients with hepatitis C virus-associated mixed cryoglobulinemia." (PMID 24945754, 2014).
Dystonia (1 paper, 2017). An abnormally increased muscular tone that causes fixed abnormal postures. "Remarkably, reminiscent of the presentation seen in our SOX5-mutated index patient, dystonia in the SOX6 deletion patient was of acute onset and combined with other hyperkinesia." (PMID 29214085, 2017).
enthesitis (1 paper, 2026). Inflammation at the site of insertion of ligaments, tendons, and other fibrous structures into bone. "Specifically inhibiting SOX5 in enthesis fibroblasts via rAAV9.HAP-1 carrying a shRNA targeting Sox5 blocked the generation of SDC1+ sheath fibroblasts in response to mechanical strain and markedly reversed the development of CXCR4hi neutrophil-mediated enthesitis." (PMID 41637585, 2026).
esophageal squamous cell carcinoma (1 paper, 2023). Esophageal squamous cell carcinoma (ESCC) is a type of esophageal carcinoma (EC) that can affect any part of the esophagus, but is usually located in the upper or middle third. "In conclusion, our study has identified down-regulated expression of SOX5 as a prognostic marker associated with poor prognosis in esophageal squamous cell carcinoma (ESCC)." (PMID 37531195, 2023).
follicular lymphoma (1 paper, 2008). Follicular lymphoma is a form of non-Hodgkin lymphoma characterized by a proliferation of B cells whose nodular structure of follicular architecture is preserved. "Moreover, translocation-driven overexpression of SOX5 has recently been described in a primary splenic follicular lymphoma, suggesting a potentially wider role for this gene in cancer." (PMID 18510758, 2008).
growth disorders (1 paper, 2021). "Interestingly, multiple sox family members (sox5, sox6, sox8, and sox18) were significantly dysregulated in shox-deficient pectoral fins together with other genes (nppa, nppc, cdkn1a, cdkn1ca, cyp26b1, and cy26c1), highlighting an important role for these genes in shox-related growth disorders." (PMID 34122528, 2021).
Hyperglycemia (1 paper, 2017). An increased concentration of glucose in the blood. "Taken together the findings point to a vicious cycle in which elevated nutrients, partly via Yy1, decrease Sox5 expression and lead to impaired insulin secretion, which in turn may aggravate the hyperglycemia." (PMID 28585545, 2017).
hyperkinesia (1 paper, 2017). "In fact, hyperkinesia and other types of motor dysfunction were recurrent, albeit variable findings among described SOX5-mutated subjects, whereas behavior deficits—as evident in both the mother and her son—were almost universally present." (PMID 29214085, 2017).
hypophosphatemia (1 paper, 2010). Lower than normal levels of phosphates in the circulating blood. "Based on Sox9 and Sox5 mRNA levels, neither the initial recruitment of cells to the callus nor their lineage commitment was effected by hypophosphatemia." (PMID 19839770, 2010).
intervertebral disc degeneration (1 paper, 2018). "Consistent with this, we found a cross-phenotypic association for the lead CBP-associated variant in SOX5 with imaging-detected lumbar intervertebral disc degeneration in a prior GWAS meta-analysis." (PMID 30261039, 2018).
ischemic stroke (1 paper, 2022). A stroke disorder caused by obstruction of blood flow to the brain, due to thrombotic (local blood clot formation) or embolic (due to a blood clot or other material traveling from another site) event. "Recent studies suggest the neuroprotective effects of SOX5 against ischemic stroke by regulating VEGF/PI3K/AKT pathway." (PMID 35070509, 2022).
leiomyosarcoma (1 paper, 2023). An uncommon, aggressive malignant smooth muscle neoplasm, usually occurring in post-menopausal women. "In the leiomyosarcoma sample, the genes involved in cell growth, survival, and proliferation (MFHAS1, YAF2, SOX5, and PAK5) were also overexpressed." (PMID 36673024, 2023).
lentivirus infection (1 paper, 2017). Virus diseases caused by the Lentivirus genus. "We next overexpressed Sox5 in intact rat islets using lentivirus infection." (PMID 28585545, 2017).
lung fibrosis (1 paper, 2023). "Given that SOX5 regulates genes in other cell types that are associated with SSc, SOX5 merits further investigation in lung fibrosis." (PMID 36835058, 2023).
mental disorder (1 paper, 2022). A disease that has its basis in the disruption of mental process. "The list of pleiotropic risk factors acting across a variety of psychiatric disorders includes such well-described candidates as NEGR1, SOX5, SORCS3, DCC, and TCF4 and indicates that MDD and PTSD are part of the greater spectrum of mental disorders with shared genetic liability." (PMID 33905376, 2022).
multiple myeloma (1 paper, 2014). "A recent study corroborates that lentiviral overexpression of murine Sox5 proteins (Sox5-BLM and L-Sox5) inhibits cell cycle progression and results in increased apoptosis of human multiple myeloma cells." (PMID 24945754, 2014).
neuroblastoma (1 paper, 2022). Neuroblastoma (NB) is the most common solid, extracranial childhood tumor. "We show that treatment of mouse neuroblastoma Neuro-2A cells with Tet34, but not its scrambled control (Tet34s), induced cell proliferation, as manifested by changes in protein levels of transcription factors and progrowth molecules cyclin D1, PCNA, Sox5, and Cdk2." (PMID 36162508, 2022).
postmenopausal osteoporosis (1 paper, 2023). Metabolic disorder associated with fractures of the femoral neck, vertebrae, and distal forearm. "For example, in human mesenchymal stem cells, SOX5 contributed to the pathology of postmenopausal osteoporosis (PMOP), and its silencing increased collagen I and decreased KLF4 expression." (PMID 36835058, 2023).
psoriasis (1 paper, 2015). An autoimmune condition characterized by red, well-delineated plaques with silvery scales that are usually on the extensor surfaces and scalp. "Although 106 TFs are encoded by psoriasis DEGs, only a fraction interacts with PREs (26/106), and several of these have not yet been examined in psoriasis studies (e.g., FOXM1, EHF, SOX5)." (PMID 25883770, 2015). "Through in silico screening of known DNA binding sites, our findings highlight proteins not yet well studied in psoriasis, including TFs (FOXM1, EHF, SOX5) and uDBPs (AVEN, RBM8A, GPAM, WISP2)." (PMID 25883770, 2015).
radiculopathy (1 paper, 2021). Disease involving a spinal nerve root (see spinal nerve roots) which may result from compression related to intervertebral disk displacement; spinal cord injuries; spinal diseases; and other conditions. "Thus, we examine if LBP with radiculopathy 12 months after an acute episode of LBP with radiculopathy is associated with the selected single nucleotide polymorphisms (SNPs); SOX5 rs34616559, CCDC26/GSDMC rs7833174 and DCC rs4384683." (PMID 35140737, 2021). "Our data did not support the hypothesis that LBP with radiculopathy 12 months after an acute episode of LBP with radiculopathy is associated with the selected SNPs; SOX5 rs34616559, CCDC26/GSDMC rs7833174 and DCC rs4384683." (PMID 35140737, 2021). "Thus, we aimed to examine if LBP with radiculopathy 12 months after an acute episode of radiculopathy is associated with the selected SNPs; SOX5 rs34616559, CCDC26/GSDMC rs7833174 and DCC rs4384683." (PMID 35140737, 2021).
renal cell carcinoma (1 paper, 2023). "GAS5 functions as a competing endogenous RNA to repress miR-21, which regulates its downstream target SOX5, resulting in the sensitivity of renal cell carcinoma to sorafenib." (PMID 37296859, 2023).
Tolchin-Le Caignec syndrome (1 paper, 2022). "Moreover, SOX5 and SOX6 heterozygous inactivating variants cause poorly studied neurodevelopmental diseases in humans (Lamb-Shaffer and Tolchin-Le Caignec syndromes, respectively; OMIM: 616803 and OMIM: 618971)." (PMID 35108528, 2022). "Moreover, given the fact that SOX5 and SOX6 heterozygous inactivating variants cause neurodevelopmental diseases in humans (Lamb-Shaffer and Tolchin-Le Caignec syndromes, respectively), our findings will also shed light on the neural alterations present in those SOXopathies." (PMID 35108528, 2022).
triple-negative breast carcinoma (1 paper, 2025). An invasive breast carcinoma which is negative for expression of estrogen receptor (ER), progesterone receptor (PR), and human epidermal growth factor receptor 2 (HER2). "SOX5 promotes tumor progression and immune evasion in triple-negative breast cancer through transcriptional activation of circ_0084653." (PMID 39889187, 2025).
tumor (42 papers, 2008 to 2026). "Overexpression of SOX5 in tumor cells is also clinically associated with poor survival of patients." (PMID 38835366, 2024). "Knockdown of SOX5 suppresses tumor growth and metastasis, and ncRNAs such as miR-143-3p that target SOX5 inhibit cancer progression, underscoring its prognostic significance." (PMID 41268614, 2026). "In a cohort of 90 patients with lung adenocarcinoma, immunohistochemical analysis revealed elevated SOX5 expression in tumor compared with adjacent non-tumor tissues." (PMID 41268614, 2026). "DHA treatment increased miR-497-5p expression and decreased SOX5 levels in tumor tissues, consistent with in vitro findings." (PMID 40697663, 2025). "By integrating molecular biology experiments and animal models, we provide the first evidence that DHA exerts its anti-tumor effects by upregulating miR-497-5p expression and suppressing the SOX5 signaling pathway." (PMID 40697663, 2025). "When the tumor reached 70–80 mm3, control siRNA and SOX5 siRNA were administered intratumorally every 3 days, and olaparib was orally administered twice daily for 3 weeks." (PMID 40274769, 2025). "In vivo, DHA dose-dependently inhibited tumor growth with miR-497-5p elevation and SOX5 suppression, effects abrogated by miR-497-5p inhibition but rescued by SOX5 knockdown." (PMID 40697663, 2025). "The miR-497-5p inhibitor and si-SOX5 reversed these effects, whereas co-treatment with miR-497-5p inhibitor and si-SOX5 restored tumor suppression." (PMID 40697663, 2025). "Significant tumor growth inhibition was observed after combining SOX5 siRNA with olaparib compared to olaparib alone (p < 0.05) and control siRNA (p < 0.05)." (PMID 40274769, 2025). "Noticeably, SOX5 siRNA alone significantly regressed tumor growth than control siRNA (p < 0.05), but the combination group exhibited a greater degree of tumor regression compared to SOX5 siRNA alone, paralleling in vitro results." (PMID 40274769, 2025). "More and more evidence shows that Sox5 acts as a tumor promoter and is abnormally high expressed in a variety of human cancers." (PMID 38835366, 2024). "In summary, the abnormally high expression of SOX5 in a variety of human malignant tumors can lead to the occurrence and development of cancer, and plays a role in almost all aspects of tumor biology (proliferation, migration, invasion, and drug resistance)." (PMID 38835366, 2024). "Knocking down or knocking out Sox5 in these cancers can inhibit cancer cell proliferation, migration, invasion, and tumor progression." (PMID 38835366, 2024). "As a transcription factor, SOX5 regulates the expression of Twist1 by binding to conserved Sox5 binding sites in the Twist1 promoter, and Twist1 promotes tumor metastasis by inducing EMT." (PMID 38835366, 2024). "In this review, the expression of SOX5 in various human cancers, the mechanism of action and potential clinical significance of SOX5 in tumor, and the therapeutic significance of Sox5 targeting in cancer were reviewed." (PMID 38835366, 2024). "For example, SOX5 was significantly upregulated in GC tissues compared to paired adjacent non-tumor tissues." (PMID 38835366, 2024). "Prior findings indicate that miR-139-5p inhibits the proliferation of PCa cells by interfering with the cell cycle, functioning as a tumor suppressor in PCa through regulation of SOX5." (PMID 37190259, 2023). "Inhibition of circ-SOX5 increased the apoptosis of tumor cells and reduced the proliferation of tumor cells through miR-502-5p/SYVN1 axis." (PMID 35048790, 2022). "Upregulated lnc-Tim3 and lnc-sox5 destroy the balance of the TME by decreasing the infiltration of antitumor CD8 + T cells aiding tumor progression." (PMID 33281872, 2020). "The qPCR analysis demonstrated that Sox5 expression was significantly higher in the BC tissues than in the non‐tumour tissues." (PMID 30983072, 2019).
tumor (continued). "Univariate and multivariate analyses showed that high SOX5 expression in adjacent non-tumor tissues was an independent prognostic factor for poor survival of LAC patients (P <0.05)." (PMID 29541384, 2018). "We also discovered that SOX5 levels in paracancerous tissues correlated to tumor size and poor prognosis." (PMID 29541384, 2018). "Patients with lower SOX5 expression in LAC tissues had longer survival time than those with high SOX5 expression (P < 0.05), and the same correlation was found in adjacent non-tumor tissues (P < 0.05)." (PMID 29541384, 2018). "In this study, the function analysis of the transcription factor SOX5 was not only studied in tumors but also in the tumor microenvironment." (PMID 29541384, 2018). "Western blot also showed that SOX5 is over-expressed in tumor tissues, whereas it was weakly expressed in respective non-tumor controls." (PMID 29541384, 2018). "Quantitative RT-PCR analysis showed that transcriptional expression of SOX5 is higher in tumors than the paired non-tumor controls." (PMID 29541384, 2018). "When investigating the SKCM dataset, we found SOX9, SOX2 as well as SOX6 to be down-regulated in the tumor subgroup of low SOX5 expression compared to the tumor subgroup of high SOX5 expression." (PMID 26927636, 2016). "The analysis of clinical tumor data (SKCM) revealed that higher SOX5 expression was a significant indicator for longer survival." (PMID 26927636, 2016). "Retroviral insertions were present in the mouse homologs of 10 genes tagged in the zebrafish tumor samples: Brd2, Cirbp, Fgf8, Hexim1, Map2k5, Mmp14, Ncoa2, Slc30a5, Sox4, and Sox5." (PMID 21533036, 2011). "Considering that SOX-5 overexpression in NPC tumors correlates clinically with poor survival it is essential to understand how SOX-5 regulates tumor progression." (PMID 20731828, 2010). "In addition to carrying the Braf gene, chromosome 6 carries several genes that are highly expressed in the LNM and tumor populations (Aqp1, Col1a2, Cav1, Cav2, Ptn, RaRes2, Fkbp9, Actg2, Ybx3, Mgp, Sox5, Kcna1, and Ptms)." (PMID 40571713, 2025). "However, the abnormal expression of SOX5 is associated with cancer of various systems, and the abnormal expression of SOX5 acts as a tumor promoter to promote cancer cell viability, proliferation, invasion, migration and EMT through multiple mechanisms." (PMID 38835366, 2024). "The abnormally high expression of SOX5 plays an important role in cancer progression and metastasis by promoting tumor cell viability, proliferation, invasion, migration and EMT, and it is also believed that the abnormally high expression of SOX5 is closely related to adverse clinical outcomes." (PMID 38835366, 2024). "The SOXD group of potential tumor suppressors in GBM comprises SOX5, SOX6, and SOX13." (PMID 37047365, 2023). "In this study, we found that miR-502-5p expression in liver tumor cells was reduced, and the inhibition of miR-502-5p expression weakened the effect of circ-SOX5 knockdown on tumor cells, indicating that miR-502-5p plays an important role in the regulatory axis of circ-SOX5." (PMID 35048790, 2022). "The protein levels of SOX5 were remarkably elevated in CRC tumor tissue and CRC cells." (PMID 33993197, 2021). "Moreover, 16 of the top 20 CIS genes had supporting fusion transcripts from at least one tumor, including Cdkn2a, Nf1, Pten, Sox6, Sox5, Spred1, and Tcf12 (all containing PB splice acceptor fusions, implying transcript termination)." (PMID 32727536, 2020). "In addition, the Western blot analysis demonstrated that the expression of Sox5 was downregulated in the tumours with circDOCK1 inhibition." (PMID 30983072, 2019). "We conclude that SOX5 expression in adjacent non-tumor tissues promotes LAC tumorigenicity." (PMID 29541384, 2018).